CCL11 (C-C motif chemokine ligand 11)
Diseases named in the same sentence as CCL11 in open-access papers (continued):
Sharing a sentence is not in itself a finding about the gene and the disease.
cancer (continued). "Elevated levels of pADPr have also been associated with the release of various chemokines, including monocyte chemoattractant protein-1 (MCP-1 or CCL2), eotaxin (CCL11), macrophage inflammatory proteins MIP-1α (CCL3) and MIP-1β (CCL4), all of which are known to promote cancer invasion." (PMID 35585513, 2022). "In addition, correlative studies in clinical trials can mechanistically explore the role of eosinophils in cancer immunotherapy by measuring baseline and on-treatment chemokines, such as CCL5/CXCL9/CXCL10/CCL11." (PMID 35954493, 2022). "Contrastingly, Aldh1a3, Ccl5, Ccl11 and Ccl7 expression were significantly higher in ALDH+ BCSCs (P2) as compared to bulk cancer cells (P0), indicating that our sorted populations were indeed pure and RNA sequencing was reflecting the expected characteristics of these BCSC populations." (PMID 35053617, 2022). "Moreover, our data demonstrated that both CCL11 and CCR3 promote the proliferation, migration, and invasion of cancer cells." (PMID 27119233, 2016). "We then examined the expression of CCL11 in several cell lines and human GBM samples, and investigated whether CCL11 and CCR3 contributed to the proliferation, migration and invasion of cancer cells in vitro." (PMID 27119233, 2016). "Compared with NHA, the levels of both CCL11 and CCR3 were increased in cancer cells." (PMID 27119233, 2016). "In cancer, CCL11 and CCR3 facilitate proliferation, migration, and invasion of cancer cells." (PMID 27119233, 2016). "Furthermore, irradiated tissue releases various chemoattractant factors, such as CCL11 or CXCL16, and promotes infiltration of lymphocytes into the cancer tissue." (PMID 25890185, 2015). "CCL11 has also been proposed as a biomarker in different types of cancers with however still little evidence that CCL11 or CCR3 expression may serve as a prognostic factor in cancer." (PMID 33608009, 2021). "Silencing CCR3 also weakened the invasion ability of cancer cells, and it could not be restored by CCL11 add back." (PMID 27119233, 2016).
inflammation (19 papers, 2011 to 2025). Aberrant reaction of the microcirculation characterized by movement of fluid and leukocytes from the blood into extravascular tissues. "We found that the chronic eosinophilic sinonasal inflammation and type 2 immune response, including the production of IL-4, IL-5, IL-13, and CCL11, were less severe in Ifnar1−/− mice than in the WT mice." (PMID 30455684, 2018). "CCL11 has been shown to promote eosinophil infiltration in allergen-induced lung inflammation." (PMID 31114590, 2019). "In our experiments, animals in the aerosol group that did not ingest the antigen displayed intense bronchial eosinophilic infiltration and high eosinophilic peroxidases (EPO) and specific IgE activity; elevated IL-4, CCL-11, and CCL-2 are associated with airway inflammation." (PMID 23724232, 2011). "Taken together, the current transcriptomic findings revealed anti-UC pharmacological targets, including the newly discovered biotargets CCL11, CCL21, CXCL3, and CXCR2, of mesalazine against DSS-induced intestinal inflammation." (PMID 34456974, 2021). "Since G-1 attenuated OVA-induced lung inflammation, we measured levels of Th1 and Th2 cytokines (IL-4, 5, and 13 and INF-γ) and an eosinophil-driving chemokine eotaxin (CCL11) in BAL fluid using ELISA." (PMID 25826377, 2015). "Eosinophil: granular leukocytes that are recruited to the lung by IL-5 and C-C chemokines (CCL11, CCL24 and CCL26) to mediate allergen-induced airway inflammation." (PMID 23828644, 2013). "Transfer of WT pDCs also limited RV-induced AHR, eosinophilic airways inflammation and production of IL-5 and CCL11 but not IL-13 release." (PMID 26108570, 2015).
neurodegenerative disease (17 papers, 2017 to 2025). A disorder of the central nervous system characterized by gradual and progressive loss of neural tissue and neurologic function. "Growing evidencemanifested the promoting effect of CCL11 on aging and aging-related diseases,especially CVDs and neurodegenerative diseases." (PMID 40026499, 2025). "Elevated levels of circulating CCL11 have been observed in patients with AD, as well as other neurodegenerative diseases." (PMID 40407975, 2025). "Recently, the role and mechanism of CCL11, an eosinophilic chemokine, in neurodegenerative diseases have been widely reported." (PMID 40026499, 2025). "Circulating levels of eotaxin-1/CCL11 have been shown to increase with aging in both animals and humans and rise in neurodegenerative diseases." (PMID 32147601, 2020). "Thus, CCL24 as well as CCL11 might be involved in aging-associated neurodegenerative diseases." (PMID 29088099, 2017). "Given the role of eotaxin in promoting neuroinflammation and cognitive decline, targeting CCL11 may offer therapeutic potential in aging and neurodegenerative diseases [1295]." (PMID 40407975, 2025). "The regulatory effect of CCL11 in neurodegenerative diseases has been widelydiscussed." (PMID 40026499, 2025). "Additionally, the effects of CCL11 on multipleaging-related diseases, such as neurodegenerative diseases and CVDs, will bediscussed, with an emphasis on the latter." (PMID 40026499, 2025). "CCL11 plays a vital role in psychosomatic and neuroinflammation, and the plasma levels of CCL11 are elevated in conditions characterized by neuroinflammation and neurodegenerative diseases." (PMID 39315093, 2024). "More comprehensive research can be done to analyze the relationship of CCL11 levels with the IL-4-to-IFN-γ ratio found in the CSF of different types of neurodegenerative diseases in pre- and post-mortem brains to build a more accurate predictive model for diagnosis." (PMID 36660076, 2022). "Likewise, increased levels of CCL11 are found in neurodegenerative diseases, where CSF concentrations of CCL11 correlate with the disease progress." (PMID 31888056, 2019). "Using human brain tissue from several neurodegenerative disease brain banks, the purpose of this study was to compare the level of expression of CCL11 in the dorsolateral frontal cortex (DLFC) among subjects with neuropathologically verified AD, CTE and normal controls." (PMID 28950005, 2017). "The observed differences in CCL11 expression with certain neurodegenerative diseases suggest that CCL11 is differentially regulated across disease states and may prove useful as a novel biomarker candidate to detect distinctive neurodegenerative diseases." (PMID 28950005, 2017). "The preliminary data presented here, describes CCL11 as another potential biomarker to aid in clinical diagnosis of CTE and to help discriminate from other neurodegenerative diseases such as AD." (PMID 28950005, 2017). "Prior research has shown the physiological importance of CCL11 to neurological function, but it may be a useful biomarker for CTE considering its ability to distinguish it among other neurodegenerative diseases." (PMID 36660076, 2022). "The CCL11/CCR3 signaling axis has been suggested to promote neuroinflammation by attracting eosinophils into the brain, which could enhance the local inflammatory response, particularly in neurodegenerative diseases such as AD and VCID [861, 1289–1291]." (PMID 40407975, 2025).
psychiatric disorder (8 papers, 2016 to 2024). A disorder characterized by behavioral and/or psychological abnormalities, often accompanied by physical symptoms. "As a marker of aging, CCL11 has also been shown to have associations with neuroinflammation, neurodegeneration, and psychiatric disorders." (PMID 36364734, 2022). "CCL11 (Eotaxin-1) is a chemokine known to enhance excitotoxicity and is associated with neurological aging in mice and psychiatric disorders in humans." (PMID 34767585, 2021). "Eotaxin-1/CCL11 has been associated with major psychiatric disorders." (PMID 29962972, 2018). "Main findings regarding eotaxin-1/CCL11 levels in major psychiatric disorders." (PMID 29962972, 2018). "Accordingly, we have described a clear association between CCL11 concentrations and age but the decreased concentrations observed in comorbid AUD patients are opposite to previous studies in psychiatric disorders, which reported increased concentrations of CCL11 in the serum of patients." (PMID 28149283, 2016). "If confirmed these pathological effects, it is tempting to propose strategies against eotaxin-1/CCL11 or its CCR3 receptor for the treatment of severe, progressing, and/or refractory cases of major psychiatric disorders." (PMID 29962972, 2018).
cardiovascular diseases (5 papers, 2018 to 2025). "Since the eosinophil is one of the primary secretors of CCL11, this further supports the idea that the downregulation of CCL11 may improve cardiovascular disease risk." (PMID 36364734, 2022). "In research on the immunomodulatory compounds in cardiovascular disease,CCL11 was selected as a crucial inflammatory immunophenotype." (PMID 40026499, 2025). "Besides the established role as an eosinophil-specific chemoattractant, CCL11 is also involved in cardiovascular diseases." (PMID 38906863, 2024).
neurological disorders (5 papers, 2015 to 2025). "Nevertheless, to date, the association between CCL11 and neurological disorders has been poorly reported." (PMID 39315093, 2024). "CCL11 triggers oxidative stress via microglial activation and potentiates glutamate-mediated neurotoxicity, which may be involved in the pathogenesis of various neurological disorders." (PMID 28173860, 2017).
bacterial infection (4 papers, 2020 to 2025). "Eosinophil-attracting chemokines such as eotaxin-1/CCL11, eotaxin-2/CCL24, and eotaxin-3/CCL26 promote host immunity against parasitic and bacterial infection." (PMID 39502090, 2024).
brain disorder (3 papers, 2020 to 2022). A disease affecting the brain or part of the brain. "More recently, CCL11 has been demonstrated to have a role in brain disorders and as an emerging molecular signature of aging." (PMID 36364734, 2022). "Recent evidence indicates that CCL-11 plays a role in brain disorders as well." (PMID 32887304, 2020).
metabolic disease (2 papers, 2017 to 2024). A congenital disorder (due to inherited enzyme abnormality) or acquired (due to failure of a metabolically important organ) disorder resulting from an abnormal metabolic process. "CCL11, which is a chemoattractant for eosinophils, basophils, neutrophils, and monocytes, can play a significant role in the regulation of many inflammatory conditions including metabolic diseases." (PMID 28396851, 2017).
cardiac disease (1 paper, 2017). "In our results, the expression of complement component C4a, C4b and inflammation genes Ccl11, Ccl8 were up expressed in older CSCs, indicated that targeting the complement system for the management of cardiac disease maybe a new therapy tool." (PMID 27980224, 2017).
immune dysfunction (1 paper, 2018). "Further analysis involving large numbers of patients in independent cohorts are needed to corroborate these associations and to understand the mechanism leading to increased sTNF-R1 and CCL11 production, as well as to determine any long-term impact on immune dysfunction." (PMID 29967620, 2018).
infectious disease (1 paper, 2017). A disorder directly resulting from the presence and activity of a microbial, viral, or parasitic agent in humans. "Several inflammatory conditions and infectious diseases also comprise the selective eosinophil chemotaxis and transendothelial migration mediated by the CC-chemokines eotaxin-1, eotaxin-2 and eotaxin-3 (CCL11, CCL24, and CCL26, respectively) via the eotaxin receptor CCR3." (PMID 29322036, 2017).
neurodevelopmental disorder (1 paper, 2021). A behavioral and cognitive disorder with onset during the developmental period that involves impaired or aberrant development of intellectual, motor, or social functions. "Specifically, cytokine and chemokine profiles alteration, which is derived from CCL2, CCL7, and CCL11 imbalance in our patients, may provoke this neurodevelopmental disorder." (PMID 34828266, 2021).
overlap syndrome (1 paper, 2023). "Overlap syndrome was associated with increased levels of the CCL11 and CD40 ligands, as well as decreased IL-10 levels." (PMID 36769452, 2023).
CCL11 also shares sentences with these, for which no sentence is quoted: ulcerative colitis (6 papers); autoimmune disease (3); co-infection (3); colorectal (3); dengue (3); eosinophilic disorders (3); Huntington disease (3); osteoporosis (3); systemic lupus erythematosus (3); tuberculosis (3); brain injury (2); dysthymia (2); psychosis (2); schistosomiasis (2); secondary progressive multiple sclerosis (2); acute appendicitis (1); acute GVHD (1); adenocarcinoma (1); age (1); aneurysm (1); autism (1); autism spectrum disorder (1); autoimmune hepatitis (1); bacterial meningitis (1); Behcet disease (1); bovine tuberculosis (1); Brain atrophy (1); brain inflammation (1); bronchiectasis (1); bullous pemphigoid (1).
A further 83 diseases each share a sentence with CCL11 in 1 paper.